THTPA (thiamine triphosphatase)
Description:
Hydrolase highly specific for thiamine triphosphate (ThTP).
Synonyms: ThTPase; THTP
Tractability: PROTAC: ubiquitination databases record sites on it; its protein half-life has been measured.
Gene: Protein-coding gene on chromosome 14 (23,555,988 to 23,560,271, forward strand). Ensembl gene ENSG00000259431.
Subcellular location: Cytoplasm
Subcellular location (Human Protein Atlas): Nucleoplasm; Nucleoli
Pathways (Reactome):
Metabolism: Vitamin B1 (thiamin) metabolism
Gene Ontology:
Molecular function: protein binding; thiamine triphosphate phosphatase activity; hydrolase activity; magnesium ion binding
Biological process: dephosphorylation; generation of precursor metabolites and energy; thiamine diphosphate metabolic process; thiamine metabolic process; thiamine diphosphate biosynthetic process; thiamine-containing compound metabolic process
Cellular component: cytosol; cytoplasm
Genetic constraint (gnomAD): Loss-of-function variants: 16 observed, 18.69 expected, observed/expected ratio (o/e) 0.86, 90% interval 0.58 to 1.3. The upper end of that interval is the gene's LOEUF score, 1.3, which puts it in group 5 of 6, group 1 being the genes least tolerant of losing a copy. Missense variants: 281 observed, 296.21 expected, observed/expected ratio (o/e) 0.95, 90% interval 0.86 to 1.05. Synonymous variants: 110 observed, 122.85 expected, observed/expected ratio (o/e) 0.9, 90% interval 0.77 to 1.05.
Homologues: Orthologues: chimpanzee THTPA (98% identical), macaque THTPA (96% identical), rabbit THTPA (81% identical), dog THTPA (79% identical), guinea pig THTPA (77% identical), pig THTPA (77% identical), mouse Thtpa (70% identical), rat Thtpa (70% identical), tropical clawed frog thtpa (40% identical), zebrafish thtpa (33% identical), zebrafish si:dkey-191c17.2 (19% identical).
Diseases named in the same sentence as THTPA in open-access papers:
THTPA is named in the same sentence as 6 diseases in open-access papers, as found by Europe PMC text mining. Sharing a sentence is not in itself a finding about the gene and the disease. The quoted sentences say what the papers report.
neuroblastoma (3 papers, 2010 to 2021). Neuroblastoma (NB) is the most common solid, extracranial childhood tumor. "We now know that in these cells, ThTP is synthesized constitutionally by AK and that THTPA is not expressed at the protein level in neuroblastoma cells in its active from, though the mRNA is present and ATP synthase does not play a significant role in ThTP synthesis in these cells." (PMID 34827643, 2021).
neoplastic disease (2 papers, 2021). "A recent study suggested that THTPA, among several other proteins, might serve as biomarkers for stratification of tumor subtypes in breast cancer." (PMID 34827643, 2021).
THTPA also shares sentences with these, for which no sentence is quoted: breast tumor (1 paper); heart failure (1); Leigh's disease (1); Thiamine deficiency (1).